MAP3K7 (mitogen-activated protein kinase kinase kinase 7)
Diseases named in the same sentence as MAP3K7 in open-access papers (continued):
Sharing a sentence is not in itself a finding about the gene and the disease.
melanoma (7 papers, 2015 to 2026). A malignant, usually aggressive tumor composed of atypical, neoplastic melanocytes. "Immune checkpoint blockade is more effective in a syngeneic mouse model of melanoma deficient in Chd1 and Map3k7 and is associated with elevated intra-tumoral CD8+ T cell numbers and activation." (PMID 41564866, 2026). "Scholars hold the view that miR-377 regulates the NF-κB signaling pathway through MAP3K7 by directly targeting E2F3 in malignant melanoma." (PMID 28947999, 2017). "Another work showed that miR-377 was a key regulator of E2F3 and MAP3K7/NF-κB pathways in melanoma progression, rendering it a potential new therapeutic target in melanoma." (PMID 28947999, 2017). "Our work shows that miR-377 is a key regulator of several cardinal pathways in melanoma progression: E2F and MAP3K7/NF-κB, rendering it a potential new therapeutic target in melanoma." (PMID 25889255, 2015). "The decrease in proliferation, migration and colony formation in melanoma cells over-expressing miR-377 can be a consequence of the down-regulation in MAP3K7 and in the activity of the NF-κB pathway." (PMID 25889255, 2015). "MAP3K7 is a key regulator of important cellular pathways associated with the growth of cancer cells (e.g. NF-κB, JNK, and p38 signaling), and was recently shown to have a role in proliferation of melanoma cells." (PMID 25889255, 2015). "MAP3K7 mRNA and protein levels were higher in melanoma cells compared to NHEM (respectively)." (PMID 25889255, 2015). "Our results suggest that miR-377 is an important negative regulator of E2F and MAP3K7/NF-kB signaling pathway in melanoma cells; it is tempting to speculate that its silencing in melanoma promotes the tumorigenic and metastatic potential of the cells through activation of these pathways." (PMID 25889255, 2015). "In melanoma cell lines, ectopic expression of miR-377 was observed to inhibit proliferation and reduce colony formation by decreasing both E2F3 and MAP3K7 protein levels." (PMID 28947999, 2017). "Ectopic stable over-expression of miR-377 in melanoma cell lines decreased both E2F3 and MAP3K7 protein levels and led to inhibition of proliferation, migration and colony formation." (PMID 25889255, 2015). "When we crossed this list with the list of down regulated mRNAs in miR-377-expressing melanoma cells, we found 4 putative transcripts with miR-377-binding sites: E2F3 (a putative target of miR-377 in 6 out of 10 software), MAP3K7 (in 4 out of 10), KRAS (in 5 out of 10) and CDK6 (in 5 out of 10)." (PMID 25889255, 2015). "We show here that the expression of miR-377 is completely silenced in melanoma cell lines and samples, and that it directly targets both the transcription factor E2F3 and MAP3K7, a tyrosine kinase along the MAPK pathway, known to be important in the activation of the NF-kB signaling pathway." (PMID 25889255, 2015). "mRNA arrays of melanoma cells over-expressing miR-377 pointed to several down-regulated mRNAs that have putative binding sites for miR-377 in their 3′UTR, of which both E2F3 and MAP3K7 were found to be direct targets of miR-377." (PMID 25889255, 2015). "Mir-377 over-expression in melanoma cells did not alter the level of MAP3K7 mRNA." (PMID 25889255, 2015).
cardiospondylocarpofacial syndrome (6 papers, 2018 to 2026). Cardiospondylocarpofacial syndrome is characterized by mitral insufficiency, conductive deafness, short stature, and skeletal anomalies (bony fusion involving the cervical vertebrae, the ossicles, and the carpal and tarsal bones). "Pathogenic variants of the MAP3K7 gene have been reported to cause two distinct but overlapping syndromes: cardiospondylocarpofacial syndrome (CSCFS) and frontometaphyseal dysplasia type 2 (FMD2)." (PMID 40909427, 2025). "Variants in the MAP3K7 gene have been linked to two distinct disorders: frontometaphyseal dysplasia type 2 (FMD2) and cardiospondylocarpofacial syndrome (CSCF)." (PMID 40909427, 2025). "Nonetheless, heart defects are part of the cardiospondylocarpofacial syndrome and we observed heart defects in 6/12 individuals with a MAP3K7 deletion." (PMID 29904178, 2018). "It is noteworthy that 2 probands have de novo variants in MAP3K7, a gene associated with cardiospondylocarpofacial syndrome but not known to cause primary CM." (PMID 39472908, 2024).
frontometaphyseal dysplasia (4 papers, 2017 to 2024). Frontometaphyseal dysplasia (FMD) belongs to the otopalatodigital syndrome spectrum disorder and is characterized by anomalous ossification and skeletal patterning of the axial and appendicular skeleton, facial dysmorphism and conductive and sensorineural hearing loss. "Frontometaphyseal dysplasia (FMD) type 2 is an autosomal dominant disorder characterized by skeletal abnormalities and caused by MAP3K7 mutation." (PMID 34716296, 2021). "In addition to CSCFS, MAP3K7 is responsible for frontometaphyseal dysplasia (FMD; OMIM # 617137) and is known to have phenotypic heterogeneity." (PMID 38383446, 2024). "In particular, heterozygous variants in MAP3K7, encoding TAK1, and its major interactor TAB2, cause cardio-spondylocarpofacial syndrome, cardio-faciocutaneousarticular syndrome and fronto-metaphyseal dysplasia." (PMID 36469137, 2023).
glioma (4 papers, 2018 to 2025). A benign or malignant brain and spinal cord tumor that arises from glial cells (astrocytes, oligodendrocytes, ependymal cells). "Expression of ISGs MX1, XAF1, or OAS2 strongly correlated with MAP3K7 dependency in DepMap glioma lines and this correlation was still present, but weaker, in 930 non-glioma cell lines." (PMID 38632238, 2024). "The predictive value of the sensitivity signature was not limited to GSCs but also correlated with MAP3K7 gene dependency in 59 DepMap glioma and non-glioma cancer cell lines." (PMID 38632238, 2024).
Frontometaphyseal Dysplasia Type 2 (3 papers, 2022 to 2026). "Crucially, MAP3K7 mutations in CSCFS are characterized by loss-of-function (LOF) effects, which contrasts mechanistically with the gain-of-function (GOF) variants that cause Frontometaphyseal Dysplasia Type 2 (FMD2)." (PMID 40909427, 2025).
leukemia (3 papers, 2018 to 2023). A malignant (clonal) hematologic disorder, involving hematopoietic stem cells and characterized by the presence of primitive or atypical myeloid or lymphoid cells in the bone marrow and the blood. "However, in an AML xenograft model MAP3K7 inhibition was found to attenuate leukemia development, indicating that MAP3K7 plays a dual role as a tumor suppressor and an oncogene depending on the malignancy." (PMID 32630372, 2020). "In 32 of 33 leukemias the deletion of MAP3K7 also included the adjacent CASP8AP2 gene." (PMID 29914415, 2018). "Accordingly, MAP3K7 deletion may render leukemia cells highly vulnerable to inactivation of the remaining MAP3K7 allele." (PMID 29914415, 2018). "In an AML xenograft model, inhibition of MAP3K7 attenuated leukemia development." (PMID 29914415, 2018). "Since Sf3b1K700E dependent missplicing in MAP3K7 was shown to result in reduced RNA and protein levels of MAP3K7 in leukaemia, we hypothesized that the reduced responsiveness to TGF-β signalling in SF3B1K700E mutant pancreas cells is caused by lower MAP3K7 levels." (PMID 37823551, 2023). "However, the multikinase inhibitor sorafenib, which has already been proven to be clinically effective in the treatment of various malignancies, inhibits MAP3K7 and may specifically target leukemias with low expression of MAP3K7." (PMID 29914415, 2018). "We assume that all three genes located between MAP3K7 and CASP8AP2 (GJA10, BACH2, MIR4464) and a variable number of adjacent genes are co-deleted in these leukemias." (PMID 29914415, 2018).
ovarian carcinoma (3 papers, 2019 to 2021). A malignant neoplasm originating from the surface ovarian epithelium. "In this study, we found that CD83 associated with MAP3K7 and activated MAPK cascades to further regulate FOXO1/p21/CDK2/CCNB1 and STAT3/DKK1 signaling pathways, thus activating proliferation and spheroid formation of ovarian cancer cells." (PMID 32823589, 2020). "Our results further show the mechanisms underlying the stimulation of proliferation and stemness of ovarian cancer cells by CD83, involving interaction with MAP3K7 and activation of MAPK signaling pathway, as well as downstream FOXO1/p21/CDK2/Cyclin B1 and STAT3/DKK1 cascades." (PMID 32823589, 2020).
pancreatic cancer (3 papers, 2015 to 2020). "GSK-3 can stabilize transforming growth factor beta-activated kinase 1 [(TAK1) a.k.a mitogen-activated protein kinase kinase kinase 7 (MAP3K7)] which plays a key role in pancreatic cancer." (PMID 32365809, 2020). "The MAP3K7 inhibitor LYTAK1 blocks NF-κB activity to increase chemotherapeutic efficacy in pancreatic cancer cells." (PMID 31214512, 2019). "Inhibition of MAP3K7 activity induces cancer cell death in pancreatic cancer, suggesting that it may be an effective target for cancer treatment." (PMID 25889255, 2015).
viral infection (3 papers, 2018 to 2022). "Among several kinases regulating the expression of DEGs expression in our analysis, genes involved in MAPK cascades (MAPK1, MAPK2, MAPK8, and MAP3K7) have roles in host response to viral infection." (PMID 33521069, 2020). "Apart from this similarity, different virus infection pathways owned their unique genes, with STAT1,RSAD2 and IRF9 in the influenza A pathway,IL-2RA,IL-2RB and CD40 in the HTLV-1 infection pathway, HCFC1, MAP3K7, SOCS3, IRF9, HMGN1, and FAS in the herpes simplex infection pathway." (PMID 35795668, 2022).
colon carcinoma (2 papers, 2020 to 2024). "They further identified JUN-terminal kinase (JNK)/MAPK8 or TAK1/MAP3K7 as transducing the signal from ERN1 to JUN; the simultaneous inhibition of this pathway and MEK results in synthetic lethality in KRAS-mutant human colon cancer cells." (PMID 38275900, 2024).
colorectal cancer (2 papers, 2024 to 2025). A primary or metastatic malignant neoplasm that affects the colon or rectum. "For instance, in colorectal cancer (CRC), up-regulation of MAP3K1, MAP3K4, MAP3K7, and MAP3K8 has been associated with tumor progression, activation of oncogenic signaling pathways, and poor prognosis, similar to findings in GC." (PMID 39901302, 2025). "For RIG-I-like receptor signaling pathway in colorectal cancer, MAPK9, MAPK14, MAP3K7, and RELA were enriched in the pathway." (PMID 39211773, 2024).
fibrosis (2 papers, 2021 to 2025). the formation of excess fibrous connective tissue in an organ or tissue in a reparative or reactive process. "MAP3K7 knockdown drives liver fibrosis and HCC via RIPK1 kinase-dependent inflammatory response." (PMID 34621787, 2021).
head and neck squamous cell carcinoma (2 papers, 2015 to 2017). A squamous cell carcinoma that arises from any of the following anatomic sites: lip and oral cavity, nasal cavity, paranasal sinuses, pharynx, larynx, and salivary glands. "Also, suppression of MAP3K7 signaling could inhibit the growth of human head and neck squamous cell carcinoma and BC cells." (PMID 28746466, 2017).
myelodysplastic syndrome (2 papers, 2022 to 2025). A clonal hematopoietic disorder characterized by dysplasia and ineffective hematopoiesis in one or more of the hematopoietic cell lines. "For example, SF3B1 mutations in myelodysplastic syndromes specifically impair the erythroid lineage by inducing mis-splicing of MAP3K7, which leads to p38 MAPK inactivation and premature downregulation of GATA1, thereby blocking terminal erythroid differentiation." (PMID 41360772, 2025). "This defect in MAP3K7 production in turn leads to hyperactivation of the NF-κB pathway that is known to drive MDS (myelodysplastic syndromes)." (PMID 35565242, 2022).
periodontitis (2 papers, 2020 to 2022). An acute or chronic inflammatory process that affects the tissues that surround and support the teeth. "Hypermethylation was found in TLR regulators genes: MAP3K7, MYD88, IL6R, RIPK2, FADD, IRAK1BP1, and PPARA in early stages of periodontitis, while advanced stages presented hypomethylation of these genes." (PMID 36233348, 2022). "The same contrary and distinctive direction from the healthy controls for moderate or severe periodontitis was found in one position for PPARA (CpG 2) and for MAP3K7 (primers MAP3K7-02:CpG 3)." (PMID 36233348, 2022).
prostate tumors (2 papers, 2015 to 2019). "Deletion of the MAP3K7 gene occurs in 30–40% of prostate tumours, and is associated with a poor clinical prognosis." (PMID 31478829, 2019). "Loss of the CHD1 and MAP3K7 genes can also promote the development of prostate tumors in the absence of SPOP mutations." (PMID 26506153, 2015).
rheumatoid arthritis (2 papers, 2007 to 2023). A chronic, systemic autoimmune disorder characterized by inflammation in the synovial membranes and articular surfaces. "MAP3K7 has also been strongly implicated in many of the processes underlying the pathology of rheumatoid arthritis and neurodegenerative diseases in which inflammation is implicated." (PMID 37936684, 2023).
steatosis (2 papers, 2022 to 2023). Increased lipid within the cytoplasm of cells. "The gene for rhomboid 5 homolog 2 (IRHom2), which encodes the rhombus protease iRhom2, activates the MAP3K7‐dependent pathway and promotes hepatic steatosis." (PMID 36943228, 2023).
Yersinia infection (2 papers, 2022 to 2024). "The other was “Yersinia infection, oas05135”(p = 0.078788), containing 5 genes (MAP3K7, PXN, DOCK1, LOC101103376, and LOC101103623) and is also associated with immunity." (PMID 38333624, 2024).
anemia (1 paper, 2023). A reduction in the number of red blood cells, the amount of hemoglobin, and/or the volume of packed red blood cells. "This study explains the mechanism by which severe anemia occurs in SF3B1 mutant MDS patients and identifies a direct role for MAP3K7 in the proper regulation of erythroid differentiation, leading to further prevention of anemia." (PMID 37007111, 2023).
ankylosing spondylitis (1 paper, 2021). An autoimmune chronic inflammatory disorder characterized by inflammation in the vertebral joints of the spine and sacroiliac joints. "Moreover, miR-10b functions as a feedback loop to suppress IL-17A by targeting MAP3K7 in ankylosing spondylitis Th17 cells." (PMID 33754012, 2021).
Arthritis (1 paper, 2023). Inflammation of a joint. "MAP3K7 inhibition was also able to diminish the expression of pain-associated mediators in synovial cells isolated from arthritis patients, suggesting its important role in managing peripheral sensitization in arthritis nociception." (PMID 37936684, 2023). "Therefore, by downregulating MAP3K7 expression, PCB may act on the amelioration of arthritis pain." (PMID 37936684, 2023).
breast adenocarcinoma (1 paper, 2025). "Mutations in the NOD1/2 signaling pathway and in DNA binding transcription factor activity, affecting genes such as MAP3K7, UBE2N, IKBKG, CHUK, and IKBKB, occurred late in breast adenocarcinoma and ovarian adenocarcinoma." (PMID 39868264, 2025).
cardiac hypertrophy (1 paper, 2017). "Cardiomyocytes derived from Map3k7-overexpressing EBs differentiate initially as small, round clusters whereas a previous study had demonstrated that Map3k7 overexpression in the ventricular myocardium resulted in cardiac hypertrophy." (PMID 29281682, 2017).
cardiomyopathy (1 paper, 2024). A disease of the heart muscle or myocardium proper. "Rare PTVs in three prioritized genes, not established causes of cardiomyopathy, were found to be associated with binary diseases outcomes (MAP3K7 and NEDD4L with DCM) in at least one cohort and with quantitative traits (NEDD4L, MAP3K7 and SSPN) in UKB." (PMID 39572783, 2024).
chronic myeloid leukemia (1 paper, 2022). "Western blot results confirmed that UNC13B may modulate the apoptosis and proliferation of arsenic trioxide-resistant chronic myeloid leukemia cells through the mediation of MAP3K7, CDK4, and PINK1." (PMID 35707364, 2022).
chronic myelomonocytic leukemia (1 paper, 2022). A myelodysplastic/myeloproliferative neoplasm which is characterized by persistent monocytosis, absence of a Philadelphia chromosome and BCR/ABL fusion gene, fewer than 20 percent blasts in the bone marrow and blood, myelodysplasia, and absence of PDGFRA or PDGFRB rearrangement. "Similar to our findings, the expression levels of ABCB7 and MAP3K7 were significantly lower in SF3B1MUT-MDS patients than in SF3B1WT-MDS patients, which was also confirmed for the cohort excluding CMML (Chronic myelomonocytic leukemia) and RAEB (Refractory anemia with excess blasts)." (PMID 36028755, 2022).
chronic obstructive pulmonary disease (1 paper, 2023). A chronic and progressive lung disorder characterized by the loss of elasticity of the bronchial tree and the air sacs, destruction of the air sacs wall, thickening of the bronchial wall, and mucous accumulation in the bronchial tree. "XFPC may regulate autophagy by down-regulating the expression of CSF1, MAPK9, MAP3K7, and AKT3, thus achieving the purpose of treating chronic obstructive pulmonary disease." (PMID 37274101, 2023).
deafness (1 paper, 2025). An inherited or acquired condition characterized by the complete loss of the ability to hear from one or both ears. "The clinical presentation of these patients with MAP3K7 variant includes facial dysmorphism, growth retardation, brachydactyly with carpal/tarsal synostosis, posterior cervical vertebral fusion, congenital heart defects and deafness with inner ear malformations." (PMID 40909427, 2025).
endometriosis (1 paper, 2024). The growth of functional endometrial tissue in anatomic sites outside the uterine body. "The PPI network analysis reveals hub genes, including BCL2, CCNA2, CDK7, EGF, GAS6, MAP3K7, and TAB2, which emerge as pivotal players in endometriosis progression." (PMID 39108650, 2024).
helminth infections (1 paper, 2025). "MAP3K7, a central regulator of immune signaling pathways, modulates host responses to helminth infections by influencing NF-κB activity." (PMID 40150341, 2025). "Studies investigating the role of MAP3K7 in parasite resistance have highlighted its significance in involving immune responses against helminth infections." (PMID 40150341, 2025).
Intellectual disability (1 paper, 2021). "In addition, despite no reports of intellectual disability in patients carrying FLNA mutation, there are several reports of intellectual disability in cases with MAP3K7 mutation." (PMID 34716296, 2021).
ischemic stroke (1 paper, 2019). A stroke disorder caused by obstruction of blood flow to the brain, due to thrombotic (local blood clot formation) or embolic (due to a blood clot or other material traveling from another site) event. "Interestingly, effectors of MAP4K4 have been proposed as therapeutic targets in cardiovascular disease and neuronal injury: at least in preclinical studies, inhibiting TAK1/MAP3K7 is protective in ischemic stroke." (PMID 30853557, 2019).
keloid (1 paper, 2021). An irregularly shaped, elevated mark on the skin caused by deposits of excessive amounts of collagen during wound healing. "Although the clinical manifestations of FLNA and MAP3K7 mutations are similar, cases with MAP3K7 mutation are more likely to display keloid formation, characteristic facial features, hearing impairment, scoliosis, and cervical fusion." (PMID 34716296, 2021).
lymphedema (1 paper, 2014). Excess fluid collection in tissues, causing swelling. "This SHIP2 mutation also overlaps with a mutation of a gene within the MAPK/ERK signaling pathway, MAP3K7, in 5 individuals with lymphedema." (PMID 25383712, 2014). "Out of these 7 subjects with MAP3K7 mutation (Hg19 chr6:91229032; T> C) 5 of them were diagnosed with lymphedema (except Subjects #9 and 12) and also harbored the T180A SHIP2 mutation." (PMID 25383712, 2014).